NRP1 (neuropilin 1)
Diseases named in the same sentence as NRP1 in open-access papers (continued):
Sharing a sentence is not in itself a finding about the gene and the disease.
pancreatic cancer (55 papers, 2005 to 2025). "We have previously reported that the miR-141/NRP-1 axis was associated with clinicopathology and contributed to the growth and metastasis of pancreatic cancer." (PMID 33912463, 2021). "The present study has demonstrated that the miR-141/NRP-1 axis is associated with the clinicopathology and contributes to the growth and metastasis of pancreatic cancer." (PMID 31572065, 2019). "Because NRP-1 only binds to VEGF165, one of the several isoforms of VEGF-A, it is possible that the binding of VEGF165 to NRP-1 causes cell progression in these pancreatic carcinoma cells." (PMID 20214829, 2010). "Neuropilin-1 overexpression in pancreatic cancer cell lines is associated with (a) increased constitutive MAPK signalling, (b) inhibition of anoikis, and (c) chemoresistance." (PMID 15956974, 2005). "This study provides evidence that altering the level of NRP-1 in pancreatic cancer cell lines causes functional changes relevant to tumour cell survival." (PMID 15956974, 2005). "This study underlines the potential of novel anti‐NRP‐1 therapy that could reduce pancreatic tumor fibrosis and subsequent progression." (PMID 30216699, 2018). "Having demonstrated that NRP-1 overexpression provides a survival advantage for FG cells exposed to two chemotherapeutic agents, we sought to determine whether decreased NRP-1 expression would render pancreatic cancer cells more susceptible to these drugs." (PMID 15956974, 2005). "Further, NRP1 expression is positively associated with prostate-specific antigen and Gleason score in prostatic cancer, while overexpression may contribute to autocrine-paracrine interactions in pancreatic cancer." (PMID 34249735, 2021). "However, in pancreatic cancer, the mechanisms underlying the function of NRP-1 in cell proliferation and metastasis and the involvement of regulatory upstream miRNAs remain unclear." (PMID 31572065, 2019). "Terms involved in cancer also appeared as enriched, including “MicroRNAs in cancer” (log (q) = −2.05), “Signaling by ALK in cancer” (log (q) = −2.04), and “NRP1 triggered signaling pathways in pancreatic cancer” (log (q) = −1.57)." (PMID 40282383, 2025). "Multiple studies have shown that NRP-1 expression was significantly increased in hypoxia-primed cervical and pancreatic cancer cells." (PMID 41035776, 2025). "In pancreatic cancer cells, which express relatively high levels of NRP1, the suppression of endogenous NRP1 completely abolished HGF-mediated cell invasion." (PMID 39769452, 2024). "Neuropilin-1 (NRP-1) is negatively regulated by miR-141, a potential biomarker in pancreatic cancer management." (PMID 38559560, 2024). "Neuropilin-1 (NRP-1) is a receptor that is upregulated in pancreatic cancer cells and endothelial cells in the TME." (PMID 37601380, 2023). "Previous research indicated that NRP1 was correlated with HIF1α expression in pancreatic cancer and non-small cell lung cancer (NSCLC)." (PMID 36841806, 2023). "IL6 upregulation has also been correlated with upregulation of NRP1 in pancreatic cancer cells suggesting their mutual involvement with pro-inflammatory pathways and cancer development." (PMID 37953774, 2023). "explained a potential mechanism in their study: SLC39A4 mediates pancreatic cancer cell growth by upregulating the expression of neuropilin‐1 (NRP‐1), vascular endothelial growth factor (VEGF), and matrix metalloproteases (MMPs) in cell lines and xenografts." (PMID 33783998, 2021). "Only in pancreatic cancers, a high expression of NRP1 correlates with reduced vascularized areas, decreased tumor growth, and improved survival." (PMID 32766254, 2020). "Although different methods are used, the experimental results are consistent with our results that NRP1 silencing can inhibit the proliferation and migration of pancreatic cancer cells." (PMID 32472711, 2020).
pancreatic cancer (continued). "In pancreatic cancer, NRP1 is negatively regulated by miR-141, a member of the miR-200 family, and the miR-141/NRP1 axis represents a potentially valuable diagnostic and therapeutic target for this tumor." (PMID 31898520, 2020). "In pancreatic cancer, NRP1 increases resistance to gemcitabine and 5-fluorouracil by activating the MAPK signaling pathway." (PMID 32766254, 2020). "We first detected the expression levels of NRP-1 protein and mRNA in a panel of human pancreatic cancer cells and pancreatic duct epithelial HDPE6C7 cells." (PMID 31572065, 2019). "Specifically, NRP-1 is highly expressed in pancreatic cancer tissues and cells that express lower levels of miR-141, whose expression is negatively correlated with NRP-1." (PMID 31572065, 2019). "By binding to the 3′UTR of NRP-1 gene, miR-141 dysregulates the expression of NRP-1, resulting in inhibition of the proliferative and migratory properties of pancreatic cancer cells and growth of established pancreatic tumors in mice." (PMID 31572065, 2019). "HDPE6C7 cells expressed significantly lower levels of NRP-1 than any of the pancreatic cancer cells." (PMID 31572065, 2019). "The expression of both NRP-1 mRNA and protein was negatively correlated with that of miR-141 in pancreatic cancer tissues by using a Pearson test." (PMID 31572065, 2019). "In pancreatic cancer tissues and cells, the expression level of NRP-1 was negatively correlated with that of miR-141." (PMID 31572065, 2019). "We further performed qRT-PCR analyses to detect the expression levels of NRP-1 miRNA and miR-141 in 23 pairs of frozen pancreatic cancer tissues and corresponding adjacent normal pancreatic tissues." (PMID 31572065, 2019). "Here we have shown that the expression level of NRP-1 is positively correlated with lymph metastasis of pancreatic cancer, underpinning the critical role of NRP-1 in metastasis." (PMID 31572065, 2019). "In this study, we have further confirmed the high expression level of NRP-1 in clinical pancreatic cancer tissues and its correlation with several clinicopathological characteristics." (PMID 31572065, 2019). "Pancreatic cancer tissues expressed significantly higher levels of NRP-1 mRNA and significantly lower levels of miR-141, compared with adjacent normal pancreatic tissues." (PMID 31572065, 2019). "The expression level of miR-141 was also negatively correlated with that of NRP-1 protein and mRNA in pancreatic cancer cells." (PMID 31572065, 2019). "The role of NRP-1 in cancer progression has been shown in many types of cancer including pancreatic cancer." (PMID 31572065, 2019). "NRP-1 was highly expressed in pancreatic cancer tissues compared with normal pancreatic tissues, and its expression levels were positively correlated with tumor grade, lymph metastasis and AJCC staging." (PMID 31572065, 2019). "In pancreatic cancer mouse models with NRP-1 overexpression (BxPC-3 and MIA PaCa-2), gemcitabine coadministered with iRGD showed enhanced tumor penetration and anticancer ability in comparison with gemcitabine alone as confirmed by pancreatic cancer models." (PMID 31346334, 2019). "By using immunohistochemistry, we found that pancreatic cancer tissues expressed higher but variable levels of NRP-1 protein, whereas normal pancreatic tissues from adjacent areas of tumors had weak NRP-1 expression." (PMID 31572065, 2019). "Li et al39 demonstrated enhanced proliferation mediated by endogenously overexpressed NRP‐1 in PANC‐1 pancreatic cancer cell line." (PMID 30216699, 2018). "In pancreatic cancer cells, NRP-1 overexpression induced constitutive MAPK signaling and chemoresistance, and inhibited anoikis." (PMID 29728077, 2018). "Studies have demonstrated that NRP-1 knockdown increases chemosensitivity towards chemotherapeutic drugs in a variety of cancer cells, including pancreatic cancer cells." (PMID 27542226, 2016).
pancreatic cancer (continued). "Nrp1 was found to interact with β1 integrin in pancreatic carcinoma cells and to be important for integrin‐mediated anchorage‐independent growth and adhesion." (PMID 25975775, 2016). "NRP2, an isoform of NRP1, was previously shown to transduce the activation of Akt in pancreatic cancer cells." (PMID 26209534, 2015). "Akashi’s report showed that pancreatic cancer models over-expressing NRP-1 are sensitive to iRGD co-administration." (PMID 26066322, 2015). "Although several types of tumor cells express VEGF-A and its receptors, the VEGF-A receptor neuropilin-1 (NRP-1) is only expressed in the pancreatic carcinoma cell lines Panc-1 and MIA PaCa-2." (PMID 20214829, 2010). "The role of NRP-1 expression in mediating chemoresistance was of particular interest, since most chemotherapeutic agents have limited efficacy in patients with pancreatic cancer." (PMID 15956974, 2005). "Chemosensitivity to gemcitabine or 5-fluorouracil (5-FU) was assessed by MTT assay in pancreatic cancer cells following NRP-1 overexpression or siRNA-induced downregulation of NRP-1." (PMID 15956974, 2005). "In summary, this study demonstrates that overexpression of NRP-1 in a pancreatic cancer cell line increased MAPK signalling through both the ERK and JNK pathways in an autocrine fashion." (PMID 15956974, 2005). "Since FG cells express relatively low levels of NRP-1 at baseline, we utilised the Panc-1 cell line, a human pancreatic cancer cell line with endogenously high levels of NRP-1 to develop clones with downregulated NRP-1 expression, utilising siRNA technology." (PMID 15956974, 2005). "MiR-141/NRP-1 axis is one of the potentially valuable targets in pancreatic cancer treatment." (PMID 38559560, 2024). "With the iRGD peptide (targeting neuropilin-1 expressed on pancreatic cancer cells), MRI can detect neuropeptide-1 positive cells expressed on pancreatic cancer cells as well as significantly-enhanced signal of pancreatic cancer." (PMID 37188192, 2023). "We checked the expression of the NRP1 in different cell types in pancreatic cancer." (PMID 35785187, 2022). "Drugs targeting VEGFR2 or NRP1 may inhibit pancreatic cancer glycolysis and represent a new strategy to treat pancreatic cancer." (PMID 35493517, 2022). "Neuropilin1 (NRP1) participates in cancer cell proliferation, migration, and metastasis as a multifunctional co‐receptor by interacting with multiple signal pathways, but few studies have addressed the precise function of NRP1 in pancreatic cancer (PACA) cells." (PMID 32472711, 2020). "In addition, the expression level of NRP-1 correlates inversely with survival of pancreatic cancer patients." (PMID 31572065, 2019). "The results indicate that NRP-1 may promote the migration of pancreatic cancer cells by enhancing EMT." (PMID 31572065, 2019). "In addition, NRP-1 depletion was shown to inhibit the migration of pancreatic cancer cells in vitro, tumor angiogenesis and liver metastasis in animal models." (PMID 31572065, 2019). "In investigating the regulatory upstream miRNAs, we have for the first time revealed that the high expression of NRP-1 in pancreatic cancer is attributed to the lower expression of miR-141, which negatively regulates the expression of NRP-1 by binding to the 3′-UTR of NRP-1 gene." (PMID 31572065, 2019). "The present results suggest that the miR-141/NRP-1 axis may be valuable biomarkers and potential therapeutic targets for pancreatic cancer." (PMID 31572065, 2019). "In addition, overexpression of miR-141 showed a similar effect as NRP-1 depletion upon the migration and EMT of pancreatic cancer cells through its dysregulation of NRP-1 and regulation on the downstream molecules." (PMID 31572065, 2019). "We genetically modified BxPC-3 cells, which were shown to express the highest level of NRP-1 among available pancreatic cancer cell lines, by transfecting them with an NRP-1 shRNA or a scrambled control (Sc) shRNA vector, generating BxPC-NRPlow or BxPC-Sc cells, respectively." (PMID 31572065, 2019).
pancreatic cancer (continued). "The present results indicate that NRP-1 is negatively regulated by miR-141 and the miR-141/NRP-1 axis may serve as potentially valuable biomarkers and therapeutic targets for pancreatic cancer." (PMID 31572065, 2019). "Given the negative regulatory role of miR-141 on NRP-1 expression and the inhibitory effects of NRP-1 depletion on pancreatic cancer we further investigated whether miR-141 could act as a tumor suppressor on pancreatic tumors." (PMID 31572065, 2019). "In addition to NRP‐1, SEMA3a and plexins are overexpressed in pancreatic cancer and are correlated with poor patient outcome." (PMID 30216699, 2018). "Overall, we observed a robust positive correlation between NRP-1 expression, EndMT markers and pro-fibrotic genes in human PDAC tissue, suggesting a previously undetermined role of NRP-1 in regulating EndMT and associated fibrosis in pancreatic tumors." (PMID 27542226, 2016). "Finally, the precise function of NRP-1 in TGFβ-mediated EndMT becomes highly relevant, given the importance of the pro-fibrotic cytokine in tumor progression, and the involvement of NRP-1 in pancreatic cancer and EMT." (PMID 27542226, 2016). "In conclusion, we provide herein for the first time, solid evidence of a novel anti-NRP-1 therapy that could lead to a reduction in pancreatic tumor fibrosis and growth via a regulatory effect on TGFβ1-induced EndMT." (PMID 27542226, 2016). "Moreover, several growth factors and inflammatory cytokines are involved in NRP regulation too: In pancreatic cancer cells, IL-6 enhances NRP1 expression whereas IL-8 increases NRP2 expression via activation of ERK1/2 pathway." (PMID 24212788, 2011). "The notion that NRP1 may play a role in mediating chemoresistance is supported by the finding that overexpression of NRP1 promotes chemoresistance in human FG pancreatic cancer cells." (PMID 20087344, 2010). "Targeting NRP-1 in pancreatic cancer cells may downregulate survival signalling pathways and increase sensitivity to chemotherapy." (PMID 15956974, 2005). "We hypothesised that NRP-1 expression by pancreatic cancer cells contributes to the malignant phenotype." (PMID 15956974, 2005). "We hypothesised that NRP-1 expression on pancreatic cancer cells contributes to the malignant phenotype." (PMID 15956974, 2005). "Given the observation that NRP-1 is expressed at higher levels in pancreatic tumours than in normal pancreatic tissue, we first chose to study the effect of overexpression of NRP-1 in a cell line with relatively low endogenous expression, the FG human pancreatic carcinoma cell line." (PMID 15956974, 2005). "However, the role of NRP1 in some tumors may be different; for example, the high expression of NRP1 in human pancreatic cancer cells Panc‐1 can reduce its incidence." (PMID 39291803, 2024). "However, little is known about the upstream mRNAs for NRP-1 in pancreatic cancer." (PMID 31572065, 2019). "Therefore, we investigated whether depletion of NRP-1 could suppress the activation of TGF-β pathway stimulated by TGF-β ligand in pancreatic cancer cells." (PMID 31572065, 2019). "Moreover, higher levels of Sema3C protein induced prostate tumor growth and inhibited apoptosis by transactivating multiple receptor tyrosine kinases via PlexinB1 and NRP1 interaction, as well as increased progression of pancreatic cancer through extracellular signal-related kinase (ERK) signaling." (PMID 31726800, 2019). "Recent studies have shown that ZIP4 upregulation in pancreatic cancer promotes the IL-6/STAT3 signalling pathway and activates the production of neuropilin-1 and vascular endothelial growth factor (VEGF), thereby enhancing tumour growth and angiogenesis." (PMID 40869403, 2025). "HIF-1α and NRP-1 protein levels were both increased after VEGF-A165 stimulation and NRP-1 silencing by shRNA reduced glycolysis in pancreatic cancer cells." (PMID 32085654, 2020).
pancreatic cancer (continued). "NRP-1 has been demonstrated to be a co-receptor interacting TGF-β and the activation of TGF-β pathway promotes EMT of pancreatic cancer cells." (PMID 31572065, 2019). "NRP-1 depletion inhibited the proliferation, migration and EMT of pancreatic cancer cells, and suppressed their ability to form tumors and to metastasize to livers." (PMID 31572065, 2019). "The expression levels of NRP-1 were positively correlated with tumor grade, lymph metastasis and AJCC staging of pancreatic cancer." (PMID 31572065, 2019). "Expression levels of NRP1, NRP2 and GIPC1 in nine pancreatic carcinoma cell lines were tested by RT-qPCR and revealed major differences." (PMID 31664117, 2019). "Recent studies of pancreatic cancer reported that ZIP4 activates the IL-6/Stat3 pathway via CREB, leading to increased expression of neuropilin-1, vascular endothelial growth factor, and matrix metalloproteases." (PMID 20957146, 2010). "Neuropilin-1 (NRP-1) is highly expressed in ovarian, breast, prostate, and pancreatic cancers." (PMID 39861688, 2024). "Furthermore, the effects of the NRP1 inhibitor on the in vivo growth and progression of PAAD were investigated using the orthotopic pancreatic tumor-bearing nude (immunodeficient) and C57BL/6 (immunocompetent) mouse models." (PMID 37190154, 2023). "Targeting IL-6 in acupuncture treatment of pancreatic cancer is a promising research direction, which may involve IL-6/STAT3 axis, DNMT1-induced SOCS3 methylation, NRP-1, etc." (PMID 36105933, 2022). "NRP1 are not only expressed in pancreatic cancer but also in macrophages/monocytes, this suggests that SEMA3C could affect the macrophage polarization by binding the NRP1 expressed in macrophages." (PMID 35785187, 2022). "In addition to its function in cell proliferation, SLC39A4 is reported to upregulate the expression of VEGFs in pancreatic cancer by upregulating its receptor NRP‐1, revealing an autocrine signaling pathway involving the ZIP4–VEGF–NRP‐1 axis." (PMID 33783998, 2021). "Therefore, the present study was designed to seek potential miRNAs that regulate NRP-1 and investigate how miRNA-regulated NRP-1 contributes to the clinicopathology, growth and metastasis of pancreatic cancer." (PMID 31572065, 2019). "We have further shown that miR-141 could inhibit the proliferation of pancreatic cancer cells by upregulating p27 and downregulating CDK2 and cyclin E through its regulatory effects on NRP-1." (PMID 31572065, 2019). "NRP-1 depletion and/or miR-141 mimics counteracted the activation of the TGF-β pathway stimulated by TGF-β ligand, resulted in sequential suppression of EMT of pancreatic cancer cells." (PMID 31572065, 2019). "We now consider the NRP-1 protein, a coreceptor for the vascular endothelial growth factor (VEGF) which is upregulated in a large variety of cancers including lung tumors, gastrointestinal metasteses and pancreatic carcinomas." (PMID 24669769, 2014). "Indeed, NRP1 potentiates HGF and FGF2 induced proliferation, survival, invasion in human umbilical vein endothelial cells (HUVEC), glioma cells, pancreatic cancer cells." (PMID 24212788, 2011). "Our laboratory and others have shown that NRP-1 is overexpressed in a variety of pancreatic tumour specimens and cell lines but not in nonmalignant pancreatic tissue." (PMID 15956974, 2005). "αv integrins and NRP-1 are also overexpressed in the vessels and stroma of human tumours, including HCC,20,46, 47, 48 and the iRGD-induced tumour uptake has been demonstrated in mice bearing patient-derived xenografts of pancreatic cancer, as well as ex vivo with human surgical tumour explants." (PMID 38889481, 2024).